LBP (lipopolysaccharide binding protein)
Description:
Plays a role in the innate immune response. Binds to the lipid A moiety of bacterial lipopolysaccharides (LPS), a glycolipid present in the outer membrane of all Gram-negative bacteria. Acts as an affinity enhancer for CD14, facilitating its association with LPS. Promotes the release of cytokines in response to bacterial lipopolysaccharide.
Synonyms: BPIFD2
Tractability: Antibody: UniProt places it where antibodies can reach, with high confidence; its Gene Ontology location is reachable by antibodies, with high confidence; UniProt predicts a signal peptide or a membrane-spanning region.
Gene: Protein-coding gene on chromosome 20 (38,346,482 to 38,377,511, forward strand). Ensembl gene ENSG00000129988.
Subcellular location: Secreted; Cytoplasmic granule membrane
Pathways (Reactome):
Immune System: Interleukin-4 and Interleukin-13 signaling; Regulation of TLR by endogenous ligand; Toll Like Receptor 4 (TLR4) Cascade; Transfer of LPS from LBP carrier to CD14
Gene Ontology:
Molecular function: coreceptor activity; lipopeptide binding; lipopolysaccharide binding; lipoteichoic acid binding; molecular carrier activity; protein binding; signaling receptor binding; lipid binding
Biological process: acute-phase response; cell surface pattern recognition receptor signaling pathway; cellular response to lipopolysaccharide; cellular response to lipoteichoic acid; defense response to Gram-negative bacterium; defense response to Gram-positive bacterium; detection of molecule of bacterial origin; lipopolysaccharide transport; lipopolysaccharide-mediated signaling pathway; macrophage activation involved in immune response; negative regulation of tumor necrosis factor production; positive regulation of interleukin-6 production; positive regulation of interleukin-8 production; positive regulation of macrophage activation; positive regulation of toll-like receptor 4 signaling pathway; positive regulation of tumor necrosis factor production; response to lipopolysaccharide; cellular defense response; innate immune response; opsonization; positive regulation of respiratory burst involved in inflammatory response
Cellular component: cell surface; extracellular exosome; extracellular region
Genetic constraint (gnomAD): Loss-of-function variants: 42 observed, 45.3 expected, observed/expected ratio (o/e) 0.93, 90% interval 0.72 to 1.2. The upper end of that interval is the gene's LOEUF score, 1.2, which puts it in group 5 of 6, group 1 being the genes least tolerant of losing a copy. Missense variants: 531 observed, 565.81 expected, observed/expected ratio (o/e) 0.94, 90% interval 0.87 to 1.01. Synonymous variants: 208 observed, 235.58 expected, observed/expected ratio (o/e) 0.88, 90% interval 0.79 to 0.99.
Homologues: Orthologues: chimpanzee LBP (98% identical), dog LBP (79% identical), macaque LBP (79% identical), pig LBP (74% identical), guinea pig LBP (68% identical), mouse Lbp (68% identical), rabbit LBP (67% identical), rat Lbp (63% identical), tropical clawed frog bpi (42% identical), tropical clawed frog bpi.4 (42% identical). Paralogues in human: BPI (44% identical), PLTP (23% identical), BPIFC (23% identical), CETP (21% identical), BPIFB3 (20% identical), BPIFB6 (20% identical), BPIFB4 (19% identical), BPIFB2 (17% identical), BPIFB1 (14% identical), BPIFA3 (8% identical), BPIFA1 (8% identical), BPIFA2 (6% identical).
Diseases named in the same sentence as LBP in open-access papers:
LBP is named in the same sentence as 254 diseases in open-access papers, as found by Europe PMC text mining. Sharing a sentence is not in itself a finding about the gene and the disease. The quoted sentences say what the papers report.
Sepsis (87 papers, 2006 to 2026). Sepsis is defined as life-threatening organ dysfunction caused by a dysregulated host response to infection. "Several studies have reported that plasma/serum levels of LBP are significantly elevated in patients with conditions associated with systemic inflammatory responses, sepsis, as well as acute and chronic infections." (PMID 39189262, 2024). "Evidence is accumulating that specific SNPs in the LBP gene are associated with a different course of many infections, including sepsis, infectious complications, and some organs infectious diseases." (PMID 34295331, 2021). "Another study also showed that susceptibility to severe sepsis was strongly correlative with a common haplotype from the 5′-flanking region of the LBP gene." (PMID 35005033, 2021). "In terms of combinations of LBP, IL-6 and TLR, LBP A + IL-6 B +TLR A is a low-risk combination of severe sepsis (p=0.027)." (PMID 34295331, 2021). "Previous study revealed that rs2232618 polymorphism (Phe436Leu) within LBP gene is a functional variant and associated with susceptibility of sepsis in traumatic patients." (PMID 30479651, 2018). "We showed in immune-stimulated G-CSF-pretreated animals that blocking the LBP/LPS interaction with a low dose of blocking peptide (0.05 mg/kg) simultaneously with the feces suspension for sepsis induction was associated with a high survival rate." (PMID 30525057, 2018). "Our study indicated that rs2232618 in LBP gene was associated with the morbidity of trauma-related sepsis and C allele carriers had higher sepsis rate in Southwest and Southwest of China trauma patients." (PMID 30479651, 2018). "It had been suggested that the concentration of lipopolysaccharide binding protein (LBP) is associated inversely with disease severity scores and outcomes in critically ill cirrhotic patients with severe sepsis." (PMID 27861595, 2016). "Soluble interleukin-2 receptor (sIL-2R) and LBP seem to represent appropriate diagnostic tools for the postmortem diagnosis of sepsis." (PMID 27239102, 2016). "In this meta-analysis, our pooled analysis indicated that serum LBP seemed to have a moderate to low diagnostic accuracy for sepsis." (PMID 27055115, 2016). "On the contrary, a low-risk sepsis development combination was BPI B + LBP A + TLR A for both PG and PGS in comparison with CG (P <0.001; P = 0.003, respectively)." (PMID 24383711, 2014). "The high-risk combination associated with sepsis development was BPI A + LBP A + TLR A. The proportion of combined major homozygotes was significantly higher in PG compared to CG (P = 0.005)." (PMID 24383711, 2014). "A polymorphism in the BPI gene (Lys/Glu - 216) was reported to be associated with increased risk for development of sepsis but is uncorrelated with gender; while a corresponding genetic variation in LBP is related to male gender." (PMID 24391897, 2013). "It has been recently reported that a functional SNP (rs2232618) in the LBP gene is associated with susceptibility to sepsis and multiple organ dysfunction in patients with major trauma." (PMID 23349936, 2013). "In support of this, mice fed fish oil supplemented diets had elevated serum-associated LBP, a clinical biomarker of sepsis associated with mortality." (PMID 23405155, 2013). "Association of CRP and LBP changes in the plasma concentration from one time point of observation to the other during 14 days after onset of sepsis." (PMID 21901123, 2011). "During sepsis, LBP levels are modified by polymorphic genetic variation of the LBP gene, predisposing these patients to excessive inflammation during an infection and contributing to a poor outcome." (PMID 19718443, 2009). "The main finding of this study is that changes in LBP serum levels at 48 hours after the onset of severe sepsis were associated with disease severity and outcome." (PMID 19718443, 2009).
Sepsis (continued). "We have also shown that CRP, lipopolysaccharide-binding protein (LBP), and IL-6 were better diagnostic markers for infection and sepsis than procalcitonin (PCT) in the same cohort of patients." (PMID 17346334, 2007). "C-reactive protein, IL-6 and lipopolysaccharide-binding protein appear to be superior to procalcitonin as diagnostic markers for infection and sepsis in patients admitted to a Department of Internal Medicine." (PMID 16569262, 2006). "High levels of LBP were associated with a lower neutrophil respiratory burst in cirrhosis, and further studies are needed to clarify the role of LBP in patients with SIRS/sepsis and liver cirrhosis, which is associated with more severe sepsis and worse outcome." (PMID 39997462, 2025). "Briefly, polymorphisms within the LBP gene might have an intensive association with sepsis and metabolic risk, which emphasize the immense potential of LBP in clinical application." (PMID 35005033, 2021). "Moreover, rs4919510 in MIR608 and rs2232618 in the coding region of the LBP gene were both functional variants and conferred susceptibility to sepsis after trauma." (PMID 33281864, 2020). "It was reasonable to suppose the SNP affecting the expression or activities of LBP might also have influence on individual susceptibility for sepsis." (PMID 30479651, 2018). "Our analysis indicated that serum LBP has a poor degree of diagnostic accuracy for sepsis." (PMID 27055115, 2016). "Consequently, mice fed diets supplemented with ω-3 PUFA suffered from increased infection-induced mortality associated with sepsis related serum LBP, IL-15 and TNF-α." (PMID 23405155, 2013). "Thus, several studies have reported increased LBP serum levels in adult patients with sepsis caused by bacterial and fungal infections." (PMID 19718443, 2009). "Among that, Lrp5, Cyp7a1, Nfkbiz, Sigmar1, Fabp7, and Hao1 have been reported in the inflammatory response and lipid metabolic process, suggesting that these genes may play an important role in modulating sepsis-induced system inflammation in WT and LBP-deficient rats after LPS injection." (PMID 35005033, 2021). "The mechanisms mediated by LBP are a crucial player in the production of sepsis and related metabolic disorders, which makes it rational to suppose that single nucleotide polymorphisms (SNPs) within LBP gene might be determinants for interindividual susceptibility." (PMID 35005033, 2021). "This is to our knowledge the first sex-specific analysis of plasma LBP in patients with SIRS/sepsis." (PMID 39997462, 2025). "In the overall SIRS/sepsis cohort and in patients with liver cirrhosis, plasma LBP levels were positively correlated with markers of liver disease severity." (PMID 39997462, 2025). "Among the 189 patients with SIRS or sepsis, the median plasma LBP concentration was 56.4 (2.5–196.0) μg/mL." (PMID 39997462, 2025). "This shows that LBP levels are still related to inflammation in patients with SIRS/sepsis and cirrhosis, but the induction seems to be impaired, probably because of reduced hepatic synthesis." (PMID 39997462, 2025). "In comparison to controls, patients with SIRS/sepsis and liver cirrhosis had higher LBP levels (p < 0.001 for both sexes)." (PMID 39997462, 2025). "In the SIRS/sepsis cohort plasma LBP negatively correlated with albumin (r = −0.254, p = 0.002) and positively with bilirubin (r = 0.268, p = 0.001)." (PMID 39997462, 2025). "Lipopolysaccharide-binding protein (LBP) is an acute-phase protein that is highly elevated in sepsis." (PMID 39997462, 2025). "This shows that the effect of metabolic disease on serum LBP levels is small compared to its increase in SIRS/sepsis." (PMID 39997462, 2025). "In the acute stage of sepsis, hepatocytes and IECs predominantly synthesize LBP in mice, which recognizes and attaches to the lipid A part of LPS and forms the LPS-LBP complex." (PMID 39769181, 2024).
Sepsis (continued). "There have been many research studies looking for markers for the diagnosis and treatment of sepsis, including microRNAs, long noncoding RNAs, circular RNAs, pancreatic stone protein, and lipopolysaccharide-binding protein." (PMID 36199375, 2022). "We further identified plasma proteins discriminating COVID-19 and sepsis, for example LBP, lactoferrin, and lipocalin 2; and differential pathways including neutrophil degranulation, complement, AP-1/p38MAPK, TLR, renin-angiotensin, and the HSC lineage." (PMID 35216673, 2022). "Both plasma endotoxin (300 pg/ml) and lipopolysaccharide-binding protein (31.2 μg/ml) levels were elevated in the patients suffering from severe sepsis and/or septic shock." (PMID 36249809, 2022). "Other biomarkers of sepsis, such as lipopolysaccharide-binding protein (LBP), soluble trigger receptor-1 (sTREM-1), and soluble urokinase plasminogen activator receptor (suPAR) expressed on myeloid cells have low sensitivity and specificity." (PMID 36407534, 2022). "Similar to serum CRP, LBP production increases due to pro-inflammatory cytokines in inflammatory states such as sepsis and multiple organ failure." (PMID 35203200, 2022). "Combinations of LBP A + IL-6 A +TLR B and LBP B + IL-6 A +TLR A were regarded to be a high risk for sepsis (p<0.006 and p=0.012, respectively), but the proportion of patients was low (4.2% and 4.8%, respectively)." (PMID 34295331, 2021). "Increased concentrations of LBP have been observed in patients with sepsis and in healthy individuals injected with LPS as well as bronchoalveolar lavage fluids of heathy individuals and patients with lung injury." (PMID 33841412, 2021). "A significant negative correlation was observed between the effects of aging and serum lipopolysaccharide-binding protein (LBP) levels, causing a higher rate of sepsis in aged mice due to a lower level of immune response." (PMID 33439913, 2021). "A rare systematic study has been reported to detect the effect of LBP gene during LPS-induced sepsis." (PMID 35005033, 2021). "The authors concluded that both blood PCT and LBP are accurate post-mortem biomarkers for the diagnosis of sepsis-related fatalities." (PMID 33092081, 2020). "During sepsis, the increased synthesis of circulating lipopolysaccharide (LPS)-binding protein (LBP) activates LPS/TLR4 signaling in renal resident cells, leading to acute kidney injury (AKI)." (PMID 31357597, 2019). "Serial monitoring of serum CRP, PCT, IL-6, IL-1b, sIL-2R, and LBP after death has been suggested to be helpful for the postmortem diagnosis of sepsis, but more studies are needed." (PMID 31661804, 2019). "The clinical setting described here, with increased serum LBP levels in MDD patients, differs from that of sepsis and septic patients, in which massive, acute LPS exposure promotes very high LBP concentrations." (PMID 31803077, 2019). "Lipopolysaccaride binding protein (LBP), a glycosylated acute phase protein, plays an important role in the pathophysiology of sepsis." (PMID 30563044, 2018). "Therefore, LBP gene polymorphisms might have an association with sepsis susceptibility." (PMID 30479651, 2018). "During sepsis, previous studies suggested that levels of serum LBP elevated almost seven times higher than normal levels." (PMID 30479651, 2018). "Lipopolysaccharide-binding protein (LBP), a key gene in the host innate immune response, has been reported to play a crucial role in the pathophysiologic process of sepsis after major traumatic injury." (PMID 30479651, 2018). "An important acute-phase protein is the glycosylated 58-kDa lipopolysaccharide binding protein (LBP) which is upregulated in the context of a signaling pathway at the onset of LPS-induced sepsis." (PMID 30563044, 2018). "Other authors indicate high diagnostic accuracy for both lipopolysaccharide-binding protein (LBP) and PCT, considered individually and combined, in detecting sepsis-related outcomes in postmortem." (PMID 27239102, 2016).
Sepsis (continued). "Our results reveal that the pooled sensitivity of serum LBP for the diagnosis of sepsis to be sub-optimal (pooled sensitivity 0.64 and pooled specificity 0.63)." (PMID 27055115, 2016). "Based on the results of our meta-analysis, LBP had weak sensitivity and specificity in the detection of sepsis." (PMID 27055115, 2016). "During sepsis, LBP levels were found to increase to median peak levels of 30–40 μg/ml within 24 h, almost seven times higher than normal levels." (PMID 27055115, 2016). "The study points out the importance of interactions among the BPI, LBP, TLR, HSP 70 and IL-6 polymorphisms and also highlights the relevance of the combination of gene polymorphisms to sepsis outcome." (PMID 24383711, 2014). "Specific combinations of common homozygosity for BPI, LBP, TLR, HSP 70 and IL-6 variants were typical within the septic group and were associated with a high risk of sepsis development." (PMID 24383711, 2014). "Markers such as interleukin-6 (IL-6), C-reactive protein (CRP) and lipopolysaccharide binding protein (LBP) have been proposed for diagnosing or monitoring sepsis." (PMID 23398965, 2013). "Using ROC analysis we found the IG count a superior biomarker for sepsis compared to C-reactive protein, lipopolysaccharide binding protein and interleukin-6." (PMID 23398965, 2013). "The fish oil supplemented diet resulted in increased mortality during infection due to sepsis evident by the presence of serum LPS binding protein (LBP), IL-15 and TNF-α." (PMID 23405155, 2013). "CRP, PCT, IL-6 and LBP levels were significantly higher in patients with sepsis as compared to SIRS." (PMID 21687569, 2011). "During the first 14 days of postoperative sepsis, LBP plasma concentrations showed a time course that was very similar to CRP with a high concordance in the pattern of day-to-day changes." (PMID 21901123, 2011). "To compare the usefulness of CRP, PCT, IL-6, and LBP in differentiating sepsis from SIRS we used the highest level of each in the first 24 hours of admission." (PMID 21687569, 2011). "More recently, Lipopolysaccharide-binding protein (LBP) has been proposed as a sensitive marker for bacterial infection and possibly useful follow-up parameter in detection and resolution of sepsis." (PMID 21901123, 2011). "In a mixed study population with SIRS, sepsis and severe sepsis, the maximum LBP concentration during the first 3 days in the ICU was found to moderately discriminate between S and NS." (PMID 21901123, 2011). "This single-centre prospective observational study showed that serum PCT levels are more valuable than serum CRP, LBP, and IL-6 levels in discriminating sepsis from SIRS in critically ill patients." (PMID 21687569, 2011). "In our study LBP levels in sepsis patients (median 26.4 μg/ml) correlates very closely with data from Pavcnik-Arnol where LBP concentrations in SIRS patients with sepsis from population of critically ill neonates were 27.1 μg/ml." (PMID 20158885, 2010). "Increased serum LBP levels have been reported in neonatal early onset sepsis, and is reported to be a better marker in critically ill neonates and children than other markers, such as C-reactive protein, procalcitonin and interleukin-6 (IL-6)." (PMID 20158885, 2010). "They measured LBP plasma levels in 253 patients with severe sepsis and/or septic shock and reported mean LBP levels in the lower range of those not only in our series but also in other recent reports." (PMID 19718443, 2009). "Among these are acute-phase reactants such as platelet factor 4, histidine-rich glycoprotein, vitronectin, fibronectin and lipopolysaccharide-binding protein, which increase in sepsis." (PMID 19958532, 2009). "In general, our findings and those from other previous reports support the important role that LBP plays in host-defense during sepsis." (PMID 19718443, 2009). "As authors stated “CRP, IL-6 and LBP appear to be superior to PCT as diagnostic markers for infection and sepsis in patients." (PMID 19578505, 2008).